SAMHD1 (SAM and HD domain containing deoxynucleoside triphosphate triphosphohydrolase 1)
Diseases named in the same sentence as SAMHD1 in open-access papers (continued):
Sharing a sentence is not in itself a finding about the gene and the disease.
HIV-1 infection (continued). "Furthermore, SAMHD1 activation presents a pharmacologically actionable target through which HIV-1 infection can be subverted." (PMID 29764952, 2018). "Importantly, as soon as proliferating cells enter the G1 cell cycle-stage, HIV-1 infection resulted in significant reduction of RT products depending on the presence of SAMHD1 dephosphorylated at T592, while concomitantly dNTP levels are low." (PMID 29884836, 2018). "Here we investigate the impact of SAMHD1 on permissivity of macrophages to HIV-1 infection." (PMID 30656243, 2018). "By this, we challenged the hypothesis that levels of RFs investigated here (SAMHD1, p21, RISP, Tetherin) could influence the pathogenic course of HIV-1 infection and might contribute to HIV-1 control in vivo." (PMID 28953327, 2017). "A more complete understanding of SAMHD1’s role in the innate immune response to HIV-1 infection may help develop stratagems to enhance its antiviral effects and to more efficiently block HIV-1 replication and avoid the pathogenic result of viral infection." (PMID 29176984, 2017). "Evidence indicates that SAMHD1 directly participates in HIV-1 infection macrophage mediation." (PMID 27878450, 2017). "Furthermore, SAMHD1 depletion in vitro in human dendritic cells (DCs) by Vpx delivery or RNAi enhances DC activation and antigen presentation upon HIV-1 infection and facilitates T cell responses in co-culture models." (PMID 27477283, 2016). "Here we report activated CD4+ T cells without SAMHD1 expression were severely reduced, and SAMHD1 in CD4+ T cells became susceptible to SIV-Vpx mediated degradation during chronic HIV-1 infection, which was absent from uninfected donors." (PMID 27922067, 2016). "SAMHD1 could also serve as a potential target for treating the immune activation that occurs during chronic HIV-1 infection." (PMID 27922067, 2016). "HIV-1 infection leads to depletion of SAMHD1- cells in activated CD4+ T cells." (PMID 27922067, 2016). "We examined whether HIV-1 infection resulted in changes in this SAMHD1 property in HIV-1 target cells." (PMID 27922067, 2016). "For example, both the activated and resting CD4+ T cells in the peripheral blood express similar levels of SAMHD1, yet activated T cells are fully susceptible to HIV-1 infection as opposed to the resistance of resting T cells." (PMID 26134849, 2015). "SAMHD1 is a dGTP-regulated deoxynucleotide triphosphates (dNTP) hydrolase that limits the pool of dNTP available for reverse transcription, therefore reducing HIV-1 infection of myeloid cells." (PMID 25608886, 2015). "However, there is uncertainty as to the extent to which the different domains of SAMHD1 contribute to restriction of HIV-1 infection." (PMID 26431200, 2015). "SAMHD1 restricts HIV-1 infection of myeloid-lineage and resting CD4+ T-cells." (PMID 26431200, 2015). "SAMHD1 appears to be particularly important for protecting dendritic cells from HIV-1 infection." (PMID 25011104, 2014). "Subsequently, SAMHD1 was shown to restrict HIV-1 infection in resting CD4+ T cells." (PMID 24599229, 2014). "However, the precise contribution of APOBEC3A to the resistance of HIV-1 infection in myeloid cells is difficult to evaluate, as SAMHD1 imposes a strong barrier to infection in these cells and is counteracted by Vpx." (PMID 24782834, 2014). "Thus, SAMHD1 represents an additional restriction factor that interferes with HIV-1 infection, at least in a specific cell type, and that can be overcome by the virally recruited cullin4A-DDB1-DCAF1 Ub ligase." (PMID 24805990, 2014). "It is also evident from our quantitative side by side comparisons of variant proteins that the ability of SAMHD1 to inhibit HIV-1 infection is not dependent on its intracellular localization, confirming and extending previous observations." (PMID 23426366, 2013).
HIV-1 infection (continued). "Further studies of SAMHD1 function and its mechanisms of blocking retroviral pathogens will benefit the design of more effective vaccines and antiretroviral interventions against HIV-1 infection." (PMID 24523981, 2013). "Interestingly, a recent work has shown that a physical contact between DCs and CD4+ T cells is adequate to reduce SAMHD1 activity and allow HIV-1 infection of resting CD4+ T cells." (PMID 23844079, 2013). "Gelais and colleagues demonstrated that SAMHD1 restricts HIV-1 infection in monocyte-derived DCs by dNTP depletion since Vpx-mediated SAMHD1 degradation significantly increased intracellular dNTP concentrations and enhanced single-cycle and spreading HIV-1 infection in DCs." (PMID 24523981, 2013). "These latter point mutations were derived from an alanine scan screen of the SAMHD1 C terminus for mutations modulating inhibition of HIV-1 infection (data not shown)." (PMID 23426366, 2013). "Furthermore, APOBEC3A has been suggested to be a specific inhibitor of the early phases of HIV-1 infection in myeloid cells, likely functioning together with SAMHD1 to block HIV-1 replication with different mechanisms." (PMID 24523981, 2013). "In monocytes and their differentiated derivatives, as well as in quiescent cells, SAMHD1 strongly inhibits HIV-1 infection and, to a lesser extent, HIV-2 and simian immunodeficiency virus (SIV) because of their virion-associated virulence factor Vpx, which directs SAMHD1 for proteasomal degradation." (PMID 23426366, 2013). "The authors consequently claim that this SAMHD1 polymorphism probably does not contribute to the control of HIV-1 infection." (PMID 24167505, 2013). "These cells are highly refractory to HIV-1 infection, supporting the role of SAMHD1 as a RF." (PMID 24167505, 2013). "Therefore, altered SAMHD1 expression or function cannot account for the IFNα-induced restriction to HIV-1 infection seen in many cells and cell lines." (PMID 23442224, 2013). "It would have important implications for vaccine development and strategies to improve immune control if increased HIV-1 infection of myeloid cells by antagonism of the SAMHD1 would indeed lead to improved innate and adaptive immune responses that are associated with effective virus control." (PMID 23497283, 2013). "Furthermore, silencing SAMHD1 expression in post-activated resting CD4+ T-cells using specific siRNA or shRNA significantly increases HIV-1 infection, further suggesting that SAMHD1 suppresses HIV-1 infection in post-activated resting CD4+ T-cells." (PMID 23092163, 2012). "Two recent studies revealed that SAMHD1 restricts HIV-1 infection in resting CD4+ T-cells, suggesting a common mechanism of HIV-1 restriction in non-cycling cells that may contribute to viral immunopathogenesis." (PMID 23092163, 2012). "Recent studies also revealed that SAMHD1 restricts HIV-1 infection in resting CD4+ T-cells." (PMID 23231760, 2012). "Since mutations in SAMHD1 result in increased production of interferon, it can be hypothesized that SAMHD1 mediated restriction of HIV-1 infection in myeloid cells likely prevents an innate immune response." (PMID 23336082, 2012). "Vpx-mediated degradation of SAMHD1 accounts for the enhanced HIV-1 infection in myeloid cells." (PMID 23231760, 2012). "Interestingly, Vpx expression or SAMHD1 depletion increases the amount of dNTPs in macrophages, suggesting that SAMHD1 inhibits HIV-1 infection by decreasing the dNTP pool required for viral cDNA synthesis." (PMID 23336082, 2012). "The observation that the different cytoplasmic variants of SAMHD1 described in this work blocked HIV-1 infection suggested that restriction does not require nuclear localization of SAMHD1." (PMID 22691373, 2012). "Thus, it is important to analyze expression levels and the activity of ribonucleotide reductases in resting and activated CD4+ T-cells to further understand the mechanisms by which SAMHD1 regulates the dNTP pool and HIV-1 infection efficiency in these cells." (PMID 23092163, 2012).
HIV-1 infection (continued). "Next, we assessed whether Vpx-mediated HIV-1 infection also affects SAMHD1 levels in primary monocytes." (PMID 22174685, 2011). "We conclude therefore that SAMHD1 protects monocytic cells from HIV-1 infection." (PMID 22174685, 2011). "We next tested the hypothesis that the efficiency of HIV-1 infection in monocytic cells correlates directly with Vpx-mediated degradation of SAMHD1." (PMID 22174685, 2011). "We found that HIV-1 infection was 12.6-fold higher in the presence of WT Vpx, compared to mutant Vpx or empty particles, and this phenotype correlated with the degradation of SAMHD1 in these cells." (PMID 22174685, 2011). "Thus, our study demonstrates that SAMHD1 is critical for restriction of HIV-1 infection in monocytes adding SAMHD1 as a novel innate defense factor." (PMID 22174685, 2011). "Importantly, the K580R or K580Q mutation did not affect SAMHD1’s subcellular localization, protein expression, protein tetramerization, and ability to deplete the dNTP pool, suggesting that K580 is important for a dNTPase-independent restriction function of SAMHD1 against HIV-1 infection." (PMID 40277359, 2025). "It would be of interest to identify the subsets of SAMHD1 that participate in the MxB-dependent and MxB-independent restriction on HIV-1 infection and whether that explains the spatial-temporal relationship of SAMHD1 and MxB, as well as the potential cell type-specific function of SAMHD1." (PMID 40277359, 2025). "Furthermore, SAMHD1-enhanced apoptosis is linked to elevated levels of the pro-apoptotic protein BCL-2-interacting killer (BIK) in cells, which contributes to enhanced apoptosis during HIV-1 infection." (PMID 40434097, 2025). "Therefore, other cellular factors and mechanisms might be involved in SAMHD1/BIK-dependent mitochondrial apoptosis induced by HIV-1 infection." (PMID 40434097, 2025). "Similarly, SAMHD1 depletion promoted HIV-1 infection levels in PMA-differentiated THP-1 cells." (PMID 40434097, 2025). "Furthermore, mutating K580 but not K354 or K494 abolished SAMHD1 restriction on HIV-1 infection in differentiated U937 cells and BLaER1 cells." (PMID 40277359, 2025). "Therefore, we investigated whether SAMHD1 acetylation affects its ability to restrict HIV-1 infection." (PMID 39162568, 2024). "Therefore, the specific mechanism, by which SAMHD1 resists HIV-1 infection, remains elusive." (PMID 39240132, 2024). "Interestingly, while cDCs in HIV-1+ patients did show a slight upregulation of SAMHD1, which encodes an antiretroviral protein reported to be effective in inhibiting early HIV-1 infection, SAMHD1 gene expression was much more upregulated in cDCs from patients with COVID-19." (PMID 36992700, 2023). "However, SAMHD1 mutations that reduce the dNTP pool without restricting HIV-1 infection have been described, suggesting a dNTPase-independent HIV-1 restriction mechanism." (PMID 37328105, 2023). "Indeed, TRAF6 KD reduced HIV-1 infection at 24 hpi by ∼2-fold in both SAMHD1 KO and control cells." (PMID 33177202, 2021). "Therefore, we investigated the effect of SAMHD1 O-GlcNAcylation on HIV-1 infection." (PMID 33391506, 2021). "However, studies in HIV-1 infection suggested an anti-viral role beyond its dNTPase activity, indicating that SAMHD1 might be regulated by other cofactors or post-translational modifications." (PMID 34238351, 2021). "As SAMHD1 limits HIV-1 cDNA synthesis in myeloid cells, it was hypothesized that degradation of SAMHD1 by Vpx in DCs would result in productive HIV-1 infection and the synthesis of viral proteins that would directly enter antigen presentation, thereby strengthening the T-cell response to infection." (PMID 29176984, 2017). "This suggested that SAMHD1 might be playing a role in the IFN block to HIV-1 infection." (PMID 24782834, 2014). "In addition, the phosphomimetic SAMHD1 mutant T592E was unable to restrict HIV-1 infection." (PMID 24782834, 2014).
HIV-1 infection (continued). "Human blood monocytes and resting CD4+ T-cells from SAMHD1-deficient AGS patients are more susceptible to in vitro HIV-1 infection compared with normal cells, suggesting that hSAMHD1 contributes to HIV-1 restriction in non-cycling immune cells through an intrinsic mechanism." (PMID 24257155, 2013). "Taking advantage of the recent characterization of SAMHD1-mediated restriction in myeloid DC, we used Vpx-expressing lentiviral vectors in order to remove this restriction block and to allow higher levels of HIV-1 infection to be reached in DC from myeloid origin." (PMID 23311681, 2013). "Thus, additional experiments will be needed to better understand whether SAMHD1 has an effect on the infection of myeloid cells during HIV-1 infection in vivo." (PMID 23344558, 2012). "Treatment of CD4+ T cells with Virus-Like Particles (VLP) containing Vpx results in the loss of SAMHD1 expression that correlates with an increased permissiveness to HIV-1 infection and accumulation of reverse transcribed viral DNA without promoting transcription from the viral LTR." (PMID 23092122, 2012). "Importantly, CD4+ T-cells from patients with Aicardi-Goutières Syndrome harboring mutation in the SAMHD1 gene display an increased susceptibility to HIV-1 infection that is not further enhanced by VLP-Vpx-treatment." (PMID 23092122, 2012). "Moreover, monocytes and resting CD4+ T cells from AGS patients that do not express functional SAMHD1 proteins were more susceptible to HIV-1 infection." (PMID 23254112, 2012). "Quantification of three independent experiments showed that the cleavage of PARP induced by HIV-1 infection was stronger in THP-1 Ctrl and SAMHD1 KI cells than SAMHD1 KO and Lvx cells at 2 and 3 dpi." (PMID 40434097, 2025). "For example, Δψm decreased 10-fold due to HIV-1 infection in THP-1 Ctrl cells at 3 dpi, whereas in THP-1 SAMHD1 KO cells, HIV-1 infection reduced Δψm by 2.8-fold." (PMID 40434097, 2025). "SAMHD1 efficiently inhibits HIV-1 reverse transcription in macrophage-like cells, resulting in a low HIV-1 infection level that hardly induces significant apoptosis." (PMID 40434097, 2025). "A close look at the SAMHD1 structure shows that the side chains for K580, D585, and T592 share a confined space, suggesting that K580 acetylation and T592 phosphorylation may regulate the conformation of this region, which ultimately regulates the ability of SAMHD1 to block HIV-1 infection." (PMID 39162568, 2024). "The results showed that mRNA levels of already known host restriction factors which inhibit HIV-1 infection, TRIM5α, MX2, SAMHD1, SERINC3, SERINC5, IFITM2, IFITM3, ApoE, and PSGL-1 were not significantly elevated by γ-IFN." (PMID 35883685, 2022). "Currently there are several cellular proteins known as restriction factors that have been extensively studied with regards to HIV-1 infection: TRIM5α; TRIM33; SAMHD1; MARCH8, APOBEC3 proteins and tetherin." (PMID 34066177, 2021). "In contrast, TRAF6 KD reduced viral luc mRNA by 3-fold in SAMHD1 KO and by 2-fold in control cells, suggesting that TRAF6 is an important cellular component for HIV-1 infection at a replication stage between late RT and mRNA transcription." (PMID 33177202, 2021). "We previously reported that SAMHD1 KO, in dividing THP-1 cells, increases the dNTP pool and HIV-1 infection." (PMID 33177202, 2021). "Relevant to HIV-1 infection, ISGs such as the restriction factors APOBEC3, SAMHD1, TRIM5α, Tetherin, and SERINC5 are induced to restrict viral replication at multiple stages in the replication cycle." (PMID 31968566, 2020). "To confirm that LPS-mediated SAMHD1 activation/dephosphorylation is responsible for block to HIV-1 infection during IFN-independent G0 arrest, we employed SAMHD1 KD in the presence of RUXO to inhibit the effects of any secreted IFN." (PMID 32209460, 2020).
HIV-1 infection (continued). "SAMHD1 restricts HIV-1 infection in DCs, myeloid cells and resting CD4+ T cells by blocking reverse transcription due to limiting the dNTP pool - thus HIV-1 infection is prevented and efficient antiviral DC activation avoided." (PMID 33224139, 2020). "We report that while HIV-1 infection of MDMGs is attenuated, restriction to infection was alleviated upon SAM domain and HD domain-containing protein 1 (SAMHD1) degradation." (PMID 33298546, 2020). "SAMHD1 is a well-characterized HIV-1 restriction factor in macrophages and we expect that the MDMs depleted of SAMHD1 are more permissive to productive HIV-1 infection." (PMID 30732620, 2019). "Generation of cGAMP, in response to HIV-1 infection and their sensing by the adaptor protein STING to induce IFN-I, can only occur in primary human DCs or macrophages under permissive conditions when SAMHD1 is inhibited by SIV-derived Vpx." (PMID 31426525, 2019). "Consistent with this theory, HIV-1 infection of MDDC and MDM only results in cGAMP production when SAMHD1 is inhibited by pretreatment with VLPs containing Vpx." (PMID 29056936, 2017). "Above all, we see that SAMHD1 expression and SIV-Vpx mediated SAMHD1 degradation have been changed in chronic HIV-1 infection." (PMID 27922067, 2016). "Similarly, we believe it unlikely that SAMHD1 plays a more direct role in cytidine deamination, first because no such enzymatic activity has been described for this protein and second because cytidine editing lowers also upon dNs supplementation during HIV-1 infection, when SAMHD1 is present." (PMID 26496699, 2015). "This shows the importance of SAMHD1 for preventing HIV-1 infection in monocytes, well known to be naturally refractory to HIV-1 infection in vitro." (PMID 24782834, 2014). "Our results indicate that cytoplasmic SAMHD1K11A can reduce HIV-1 infection in primary MDM and is substantially less sensitive to VpxMAC mediated suppression relative to nuclear localised SAMHD1." (PMID 24712655, 2014). "The inhibitor hindered HIV-1 infection in the presence of APOBEC3G, even when Vif was expressed, and it stopped HIV-2 infection in the presence of SAMHD1 and Vpx." (PMID 24245672, 2013). "By contrast, overexpression of SAMHD1 in monocytic U937 cells and then differentiation with PMA inhibits HIV-1 infection in the cells." (PMID 24523981, 2013). "We next determined the effect of SAMHD1 over-expression on the intracellular dNTP pool and VSV-G-pseudotyped single-cycle HIV-1 infection." (PMID 23231760, 2012). "SAMHD1 silencing also enhances HIV-1 infection of resting CD4+ T cells, suggesting that SAMHD1 also restricts HIV-1 infection in quiescent T cells." (PMID 23344558, 2012). "This suggests that SAMHD1 has a role in HIV-1 restriction in DCs, but it is likely that additional post-entry restriction steps exist to block HIV-1 infection in DCs." (PMID 23231760, 2012). "Sterile alpha motif (SAM) and histidine-aspartate (HD) domain-containing protein 1 (SAMHD1) restricts HIV-1 infection in non-dividing immune cells, such as resting CD4+ T cells, macrophages, and dendritic cells." (PMID 40434097, 2025). "Conversely, at 4 dpi, higher luciferase activity was detected in infected Ctrl cells compared to SAMHD1 KO cells, consistent with our previous results that SAMHD1 did not inhibit HIV-1 infection at later time points in monocytic cells." (PMID 40434097, 2025). "We demonstrate that SAMHD1 enhances apoptosis induced by HIV-1 infection in dividing monocytic THP-1 and U937 cell lines, but not in differentiated macrophage-like cells." (PMID 40434097, 2025). "Unlike point mutations targeting K580, the point mutations we tested targeting K354 and K494 did not appear to have any effects on the ability of SAMHD1 to block HIV-1 infection." (PMID 39162568, 2024). "In the absence of functional CypA (CsA-treated U937 cells), SAMHD1/MX2 still inhibited HIV-1 infection." (PMID 38888311, 2024).